LOXL2 (lysyl oxidase like 2)
Diseases named in the same sentence as LOXL2 in open-access papers (continued):
Sharing a sentence is not in itself a finding about the gene and the disease.
tumor (261 papers, 2008 to 2026). "One of the important regulators for collage is lysyl hydroxylase 2 (LOXL2), which has been found to cause a transition in collagen cross‐linking in tumor stroma." (PMID 39801760, 2025). "Studies have confirmed that LOXL2 is significantly associated with tumor invasion and metastasis in a variety of malignant tumors." (PMID 40756111, 2025). "The deficiency of LOXL2 in female mice caused abnormal cell proliferation and signal transduction, leading to organ enlargement and tumor development in the uterus." (PMID 39456765, 2024). "The presence of LOXL2 mutations has a substantial effect on the progression of tumors, resulting in tumor heterogeneity." (PMID 38922489, 2024). "By combining data from various types of cancer, we extensively investigated the panorama of LOXL2 in pan-cancer and elucidated its interconnected role in tumor progression, mutational profile, immune response, and cellular senescence." (PMID 38922489, 2024). "Many studies have revealed that aberrant LOXL2 expression in multiple cancers is associated with tumor metastasis, poor prognosis, and chemoradiotherapy resistance." (PMID 39145451, 2024). "The overexpression of LOXL2 was consistently reported in numerous studies associated with tumor aggressiveness and poor prognosis in various types of cancer." (PMID 39329988, 2024). "Copper deficiency, related to decreased VEGFR2 and LOXL2, suggests potential effects on the pre-metastatic tumor environment." (PMID 37427098, 2023). "Among the different tumours, skin cutaneous melanoma and uterine corpus endometrial carcinoma exhibited the highest frequency of LOXL2 mutations (8.60% and 6.43%, respectively)." (PMID 37762708, 2023). "Extensive research with large cohorts of human tumour samples has demonstrated that dysregulated LOXL2 expression is strongly associated with poor prognosis in patients." (PMID 37762708, 2023). "In several cancers, LOXL2 is not only frequently upregulated, but its upregulation is also implicated in tumor invasiveness and metastasis." (PMID 37958410, 2023). "In most cases, the overexpression of LOXL2 has been confirmed to be associated with poor prognosis and/or dissemination, reinforcing the role of LOXL2 as a prognostic biomarker in different tumour types." (PMID 37762708, 2023). "Clinical data showed that positive LOXL2 expression was associated with tumor proliferation, so the effect of LOXL2 silencing and overexpression on ESCC cell proliferation was examined using the Cell Counting Kit-8 (CCK-8) assay." (PMID 36995521, 2023). "Over the last two decades, overexpression of LOXL2 has been consistently reported in numerous studies to be associated with tumour aggressiveness and poor prognosis in various types of cancer." (PMID 37762708, 2023). "For example, mutations in the SOD1 gene are associated with oxidative stress, and mutations in the LOXL2 gene are associated with tumor proliferation and invasion." (PMID 37886979, 2023). "LOXL2 was overexpressed in GC versus normal tissues, and overexpression of LOXL2 was associated with depth of tumor invasion, lymph node metastasis and poorer overall survival." (PMID 35126449, 2021). "High LOX and LOXL2 expression is considered a risk factor for the early occurrence of metastases, mostly due to their ability to stimulate tumor cell migration and invasion." (PMID 33669630, 2021). "This analysis signifies that the LOXL2 gene expression levels are associated with a more mesenchymal phenotype in tumor datasets." (PMID 33807227, 2021). "High LOXL2 expression was associated with more aggressive tumor behaviors, including larger tumor size, advanced T stage, and frequent distant metastasis." (PMID 34836938, 2021). "It has been well documented that LOX family members, especially LOX and LOXL2, are elevated and associated with tumor progression." (PMID 33883562, 2021).
tumor (continued). "In summary, our results supported the relevance of LOXL2 expression status in multiplatform integrative analyses, prognosis of tumor mutation density, and survival prediction in cancer." (PMID 32211324, 2020). "Aberrant expression of LOXL2 was often associated with elevated metastasis potency of tumor cells, and the outcome was reported as a poor prognosis in various kinds of malignancies including gastric cancer, head and neck squamous cancer, and breast cancer." (PMID 30809541, 2019). "Regarding ECM remodeling, Lysyl Oxidase-like 2 (LOXL2) is upregulated in tumor-associated stroma of PDAC, ESC, and HCC." (PMID 31885581, 2019). "We have previously shown that high tumor LOXL2 levels are correlated with an increase in cancer associated fibroblasts (CAFs) within tumors." (PMID 28199967, 2017). "Elevated HIF-1α and LOXL2 expression was associated with an increase in tumor grade and VM (p < 0.05)." (PMID 28449718, 2017). "Taken together our study demonstrates that the tumor microenvironment can promote DTC to acquire a CSC-like phenotype via EMT mediated by LOXL2 expression resulting in their outgrowth and loss of their luminal phenotype." (PMID 27655685, 2016). "A number of known tumour associated angiogenic genes were identified by this analysis, including interleukin 8, angiopoietin 2 and lysyl oxidase like 2, validating the approach as a method for identifying genes enriched on tumour endothelium." (PMID 26943033, 2016). "So it is expected that LOXL2-e13 causes broad changes in mRNA expression profile, including some critical tumor-related genes, enabling LOXL2-e13 to play new and specific roles in ESCC compared to its wild-type counterpart." (PMID 25254241, 2014). "LOXL2 promotes tumor cell invasion and is associated with metastasis and reduced survival of patients with various cancers." (PMID 22570691, 2012). "However, loss of LOXL2 only partially recapitulated the effect of PEAR1 on tumor cells, suggesting that the effect of PEAR1 involved additional mechanisms." (PMID 41185039, 2025). "The effects of LOXL2 on tumor infiltrated immune cells and oncogenic senescence have not yet been elucidated, it eagerly anticipates future exploration of the mechanisms underlying tumor advancement and the transition to a senescent state." (PMID 38922489, 2024). "Overall, LOXL2 could be a potential prognostic and diagnostic biomarker, and afford new thought for tumor personalized therapy." (PMID 38922489, 2024). "LOXL2 was identified as being associated with tumor progression and cellular senescence." (PMID 38922489, 2024). "In addition, the secretion of VEGFA and PDGF (platelet-derived growth factors) by tumor cells induces LOXL2 in endothelial cells of tumor-associated blood vessels, stimulating angiogenesis to vascularize the tumor." (PMID 39329988, 2024). "In this pan-cancer study, we examined the notable disparity in LOXL2 expression at the mRNA and protein levels among various cancer types and elucidated its interconnected roles in tumor progression, mutational profile, immune response, and cellular senescence." (PMID 38922489, 2024). "In pancreatic cancer, LOXL2 expression is positively associated with tumor burden and metastasis." (PMID 39555068, 2024). "Moreover, the study identified oncostatin M secreted by tumour-associated macrophages as an inducer of LOXL2 expression." (PMID 37762708, 2023). "Moreover, investigations have revealed the association of LOXL2 with various targets affecting diverse aspects of tumour progression." (PMID 37762708, 2023). "In contrast, LOXL2 overexpression appears to be the main feature linked to tumour aggressiveness." (PMID 37762708, 2023). "Additionally, the discovery of a complex network of signalling factors acting at the transcriptional, post-transcriptional, and post-translational levels has provided insights into the mechanisms underlying the aberrant expression of LOXL2 in tumours." (PMID 37762708, 2023).
tumor (continued). "Furthermore, the level LOXL2 was markedly positively associated with tumor immune cell infiltration and immune checkpoint expression in HCC." (PMID 36254230, 2022). "Aberrant activity of LOXL2 has been associated with organ fibrosis and tumor metastasis." (PMID 35682561, 2022). "One of the first things that was noticed when the link between LOXL2 overexpression and induction of tumor cells invasiveness was first established is that LOXL2 overexpression is associated with the deposition of a high concentration of collagen fibers in the tumor microenvironment." (PMID 35682926, 2022). "Finally, the Tumor Immune Estimation Resource (TIMER) was used to explore the association between LOXL2 and immune cell infiltration." (PMID 36254230, 2022). "The relationship between LOXL2 and immune cell infiltration was investigated using the timer database because the level of immune cells is associated with the proliferation and development of tumor cells." (PMID 36254230, 2022). "Interestingly, immunoblot analysis suggested that OSM-induced expression of the N-linked glycosylated form of the LOXL2 protein (105 kDa) which is secreted into the tumor microenvironment." (PMID 34011405, 2021). "And the different features in the same patient indicated that LOXL2 expression status may reflect a combination of tumor heterogeneity and tumor-associated functional phenotype and represent an opportunity to subtype stratified clustering." (PMID 32211324, 2020). "This is reminiscent of several other differentially expressed genes in CAF and warrants further analysis to determine whether LOXL2 levels may be associated with the clinic-pathologic or genomic features of the tumor." (PMID 31061140, 2019). "Moreover, in a chemical skin carcinogenesis model, Loxl2 overexpressing mice show an increased tumour burden, whereas Loxl2 deficient mice exhibit the opposite phenotype." (PMID 29953488, 2018). "Apart from investigating the hyperexpression of LOXL2 being related to poorer prognosis in different types of tumors, this study also unveiled noteworthy connections between LOXL2 and genetic mutations, infiltration of tumor immune cells, and genes in immune checkpoint pathways." (PMID 38922489, 2024). "Despite the wealth of information available on the overexpression of LOXL2 at the mRNA and/or protein level in tumours there are scarce data regarding the presence of genetic mutations of LOXL2 in human tumours that could potentially impact LOXL2 expression and/or function." (PMID 37762708, 2023). "Notably, LOXL2 has been widely linked to cancer and the acquisition of cellular malignancy, as it is overexpressed in many tumors and has an important role in tumor formation." (PMID 31462706, 2020). "In contrast, the monoclonal antibody AB0023 targeting LOXL2 demonstrates superior safety and efficacy: it simultaneously suppresses tumor metastasis and TGF-β signaling activation, showing broad applicability in both oncologic and fibrotic diseases." (PMID 41362727, 2026). "Mechanically, TRIM44 directly binds to LOXL2, affecting the stability of LOXL2, altering extracellular matrix remodeling, and affecting tumor immunity." (PMID 39915459, 2025). "Through the robust machine learning approaches, we developed a four‐gene model (MGP, LOXL2, FSTL3, and PFN2) reflecting key biological processes associated with inflammatory CAF activity and tumor aggressiveness." (PMID 41395115, 2025). "Studies have shown that lysine oxidase 2 (LOXL2) plays an important role in a variety of cancers, and its expression level is closely related to tumor invasion, metastasis and clinical prognosis." (PMID 40756111, 2025). "This is consistent with the well-established role of LOXL2, which acts both extracellularly and intracellularly to promote tumor cell growth and metastasis and to inhibit tumor cell dormancy." (PMID 41185039, 2025). "Elevated LOXL2 activity in the tumor microenvironment can promote tumor cell invasion and resistance to therapy." (PMID 40909292, 2025).
tumor (continued). "Multiplex IF staining of tumor tissues revealed that the total number of PSCs remained unchanged, but the number and the proportion of LOXL2+ PSCs were higher in the LOXL2-OE group." (PMID 40425551, 2025). "Later in the paragraph, LOXL2’s role in modulating the tumor microenvironment is discussed in more detail." (PMID 40061935, 2025). "Our data identify a mechanism underlying tumor cell dormancy and suggest CTSD and LOXL2 as targets for approaches to promote dormancy." (PMID 41185039, 2025). "Preclinical studies have demonstrated that targeting LOXL2 can reduce tumor stiffness, impair cancer cell invasion, and sensitize tumors to chemotherapy." (PMID 40661776, 2025). "Multiplex IF staining of tumor tissues from subcutaneous coimplantation experiments revealed increased infiltration of LOXL2+ PSCs in the MMA.HPSC+MIA PaCa-2 group." (PMID 40425551, 2025). "According to the grouping difference, most of LOXL2 was enriched in the Aacrophage Area and Tumor Area." (PMID 40756111, 2025). "We thereby identified PEAR1 as an endothelial transmembrane protein which promotes tumor cell dormancy in vitro and in vivo by binding and thereby inactivating the pro-proliferative proteins LOXL2 and CTSD." (PMID 41185039, 2025). "Subcutaneous coimplantation experiments further demonstrated that LOXL2 knockdown suppressed the tumor-promoting effects of MMA-induced HPSCs and reduced linear ECM alignment." (PMID 40425551, 2025). "TRIM44 directly binds to LOXL2 and regulates its stability to remodel the tumor extracellular matrix and influence tumor immunity." (PMID 40936722, 2025). "Since LOXL2 is well known to inhibit tumor cell dormancy and to promote metastasis and tumor growth, we focused our anlaysis on the function of CTSD." (PMID 41185039, 2025). "LOXL2 expression is upregulated under hypoxic conditions through HIF-1α signaling, and its activity has been associated with tumor progression and immune exclusion in HCC." (PMID 41013723, 2025). "We found that PEAR1 induces tumor cell dormancy by binding lysyl oxidase like 2 (LOXL2) and cathepsin D (CTSD), which both inhibit tumor cell dormancy and promote tumor growth and metastasis." (PMID 41185039, 2025). "Nineteen genes (44%) demonstrated loss or promoter silencing of the wildtype allele in at least one tumour, with six genes (SLC12A4, LOXL2, ZCCHC4, LLGL2, MIPOL1, SCYL3) demonstrating this in multiple samples." (PMID 39794353, 2025). "Additional studies revealed that Lysyl oxidase-like 2 (LOXL2) expression in OSCC tissues was significantly correlated with tumor clinical stage, and lymph node metastasis patient overall survival." (PMID 40061935, 2025). "Single cell sequencing data analysis showed that LOXL2 was mainly enriched in tumor cells, macrophages and stromal cells." (PMID 40756111, 2025). "As the results showed, expression of LOXL2 in tumor tissues in CMMH-treated mice were downregulated compared to those in PBS group." (PMID 38326908, 2024). "The results showed that FKBP4 and LOXL2 expression was significantly upregulated in the tumour cell lines." (PMID 38577594, 2024). "ATC-CAFs showed high expression levels of genes associated with tumor invasion (MMP14, LOXL2, and PGK1)." (PMID 38478516, 2024). "Studies have shown, in a variety of cancers, that increased expression of LOXL2 is related to epithelial-mesenchymal transition, tumor development, invasion, and metastasis and is a marker of epithelial-mesenchymal transition and poor prognosis." (PMID 38810697, 2024). "The xCELL method determined the association between the majority of the 64 immune cell subtypes and LOXL2 expression in different tumor types." (PMID 38922489, 2024). "Conversely, deficiency in LOXL2 led to increased acetylation of H3K36, which in turn increased the expression of various genes associated with tumor progression." (PMID 39456765, 2024). "The interaction of LOXL2 with proteins involved in cell adhesion and signaling pathways increases the aggressiveness of tumor cells." (PMID 39329988, 2024).
tumor (continued). "The findings suggested that LOXL2 has the ability to suppress the growth and migration of tumor cells." (PMID 38922489, 2024). "Early studies on LOXL2 have shown that LOXL2 is a cancer-promoting factor that is highly expressed in a variety of tumors and can promote the proliferation, invasion, and metastasis of tumor cells." (PMID 38810697, 2024). "Genes in CDR signature had been reported to participate in tumor immunity process, in which LOXL2 and PFKP were apparently with high index in CDRSig." (PMID 38977778, 2024). "Above all, LOXL2 has the potential to regulate stromal cells, modify the tumor immune microenvironment, and impact the response of immunotherapy in multiple tumors." (PMID 38922489, 2024). "We also revealed that lysyl oxidase–like protein 2 (LOXL2), a well-known regulator of tumor, is an endogenous ligand binding to the PEAR1-EMI domain and facilitating PEAR1 Ser891 phosphorylation, which is essential for the binding of PEAR1 to CD44." (PMID 39145451, 2024). "We previously showed that oncostatin M (OSM), derived from tumor‐associated macrophages, acts as a major inducer of the upregulation of EMT‐related genes, including LOXL2." (PMID 39297408, 2024). "Up-regulation of LOXL2 leads to metastasis in the tumour microenvironment, which results in invasive migration." (PMID 38577594, 2024). "The decrease in LAMC2 and LOXL2 secretion correlated with other phenotypic changes, including decreased clonogenicity, tumor sphere formation, spheroid growth, growth in vivo and increased drug sensitivity." (PMID 39496753, 2024). "Cox and Kaplan–Meier curve analysis indicated a significant association between elevated LOXL2 expression and an increased incidence of poor OS (15 tumor types), DSS (17 tumor types), DPI (13 tumor types), and PFI (24 tumor types)." (PMID 38922489, 2024). "Mechanistically, macrophages increase matrix stiffness by secreting oncostatin M (OSM), which upregulates LOXL2 in tumor cells." (PMID 39555068, 2024). "Our analysis revealed associations between the majority of the 64 immune cell subtypes and LOXL2 expression in various tumor types." (PMID 38922489, 2024). "Our findings indicate that LOXL2-induced N-WASP expression is a key regulator for tumor metastasis using invadopodia." (PMID 38560567, 2024). "Expression of LOXL2 in tumor tissues in AAV8-LOXL2 group were upregulated compared to those in AAV8-Ctrl group." (PMID 38326908, 2024). "Since then, numerous studies have described LOXL2 overexpression in various tumour types significantly impacting patient prognosis (refer to Section 2)." (PMID 37762708, 2023). "The use of both complementary L2-KO and L2-KI GEMMs allowed us to demonstrate a key role for Loxl2 in tumour initiation and progression in mouse and human squamous cell carcinomas." (PMID 37762708, 2023). "Overall, these data indicate that the simultaneous inhibition of BRD4S and LOXL2 successfully reduces tumor growth by suppressing TNBC cell proliferation and inducing cell death, holding exciting potential for the development of future clinical applications." (PMID 37937685, 2023). "Kazuhiko et, al. suggested that LOXL2 is probably a tumor promoter in OS that favors bone formation and promotes a more aggressive osteoblastic phenotype; cFos/LOXL2 co-expression correlated with decreased survival of OS patients." (PMID 37056396, 2023). "Given the demonstrated role of LOXL2 in tumour progression and fibrotic disease, inhibiting the classical catalytic activity of the enzyme appeared as a potential therapeutic alternative." (PMID 37762708, 2023). "This represents a great advantage in the clinical field because we can mimic low LOXL2 levels by treating with inhibitors, and effectively stop tumor growth by co‐treating with BETi." (PMID 37937685, 2023). "And High expression of LOXL2 in tumor tissues predicts poor survival in cervical cancer, neck squamous cell carcinoma, hepatoma carcinoma and other cancer patients." (PMID 36906534, 2023).